NOTCH1 (notch receptor 1)
Diseases named in the same sentence as NOTCH1 in open-access papers (continued):
Sharing a sentence is not in itself a finding about the gene and the disease.
Obesity (continued). "Overall, in this study, we reveal that SLC35D3 is involved in obesity via NOTCH1 signaling, and low adipose SLC35D3 expression in obesity might be a therapeutic target for obesity and associated metabolic disorders." (PMID 37996411, 2023). "Studies have demonstrated that adipocyte-specific overexpression of Notch1 impairs thermogenesis and insulin sensitivity, leading to classical BAT whitening, and that pharmacological inhibition of Notch1 causes WAT browning and ameliorates high-fat diet-induced obesity." (PMID 36661498, 2022). "Taken together, these data show that inhibition of Notch1 signaling can regulate the expression of fatty acid oxidation genes and may provide therapeutic strategies in obesity-induced hepatic steatosis." (PMID 26786165, 2016). "Moreover, in vitro experiments, it was proved that EGCG could promote the mitochondrial biogenesis and UCP-1 expression of adipocytes by inhibiting Notch1 expression, so as to promote the browning of white adipocytes and improve obesity." (PMID 38893431, 2024). "In addition, knockdown of Notch1 in mouse inguinal white adipose tissue mediated by orthotopic injection of AAV8-adiponectin-shNotch1 shows considerable improvement in obesity and glucolipid metabolism, which is more pronounced in adipocyte-specific Slc35d3 knockout mice than in knockin mice." (PMID 37996411, 2023). "Therefore, low SLC35D3 expression in adipose tissues might be a potential therapeutic target of obesity, and NOTCH1 inhibition could lead to greater gains." (PMID 37996411, 2023). "Similarly, in xenograft experiments where lean and obese immunocompromised mice were transplanted with human T-ALL cells, the survival advantage of obesity was more dramatic with 20% of lean and 80% of obese mice surviving over 2 months post-transplantation with NOTCH1-expressing cells." (PMID 36060800, 2022). "Taken together, knockdown of Notch1 in the IngWAT of SAKO mice showed a significant rescue effect, as shown by resistance to obesity and improved metabolism." (PMID 37996411, 2023). "New interventions targeting LEP, NOTCH1, SPRY1, PPARG, ID2, and CIDEA gene network, in addition to what already is going on, can be designed for treatment and prevention of both obesity and tumors." (PMID 35395810, 2022). "Here, the authors show that SLC35D3 promotes white adipose tissue browning through the NOTCH1 signalling pathway and SLC35D3 may be a potential therapeutic target for obesity and related complications." (PMID 37996411, 2023). "By contrast, ECM genes, VEGF signaling members Vegfa and Vegfc and Notch1 signaling genes Dll1, Jag1 and Numb were upregulated by sustained obesity in lung cap ECs but were not attenuated by a reversion diet." (PMID 36400935, 2022). "Here, UDCA led to reducing lipogenesis, gluconeogenesis, and Notch 1 signaling proteins in ob/ob mice, suggesting that UDCA plays an important role in lipid, glucose metabolism, and energy storage capacity in those with obesity." (PMID 30884843, 2019).
ischemic stroke (18 papers, 2017 to 2026). A stroke disorder caused by obstruction of blood flow to the brain, due to thrombotic (local blood clot formation) or embolic (due to a blood clot or other material traveling from another site) event. "In line with this hypothesis, Pin1 has been reported to play a key role in acute neurological conditions associated with subsequent neurodegeneration, such as ischemic stroke, where it promotes neuronal death by acting on Notch1 signaling pathway." (PMID 33083964, 2021). "γ-secretase-mediated Notch1 activation impairs neuronal function after ischemic stroke by increasing apoptosis, proinflammatory leukocyte infiltration, and microglial activation." (PMID 38137105, 2023). "In this study, we report for the first time that miR-449b/Notch1 is involved in the regulation of neurogenesis after ischemic stroke." (PMID 36009031, 2022). "In brief, LRIC suppresses miR-449b expression, thereby activating the Notch1 signaling pathway, promoting neurogenesis after ischemic stroke, and ultimately improving neural function." (PMID 36009031, 2022). "LncRNA GAS5 promotes mouse ischemic stroke through acting as a competing endogenous RNA (ceRNA) for miRNA-137 to regulate Notch1 signaling." (PMID 33461167, 2021). "It has been reported that BMSCs transplantation enhanced neurogenesis after ischemic stroke and improved osteopenia in Lupus via inhibiting Notch1 signaling." (PMID 30646897, 2019). "MSCs transplantation has been demonstrated to suppress Notch1 signaling in ischemic stroke, inflammatory bowel disease, and lupus." (PMID 30646897, 2019). "In the CNS, Notch1 signaling not only regulates microglia-mediated neuroinflammation but also participates in the process of neuronal injury in ischemic stroke." (PMID 30646897, 2019). "To further verify whether IL-17A/Notch1 signaling is involved in the process of LIPUS promoting the generation of mature OLs in ischemic stroke mice, we added IL-17A monoclonal antibody (IL-17A mAb) to inhibit IL-17A signaling." (PMID 40290135, 2025). "However, it is worth noting that the latest evidence shows that EA can activate the HIF‐1/VEGF/Notch1 signaling pathway and promote angiogenesis after ischemic stroke through exon miR‐210." (PMID 36786352, 2023). "CircRNAs also facilitated Notch1 to provide neuroprotection in ischemic stroke." (PMID 35392276, 2022). "This study aimed to investigate whether LRIC could promote neurogenesis after ischemic stroke and the role of the miR-449b/Notch1 pathway in LRIC-induced neuroprotection." (PMID 36009031, 2022). "Since Notch1 can be controlled by circRNAs in ischemic stroke, further studies are needed to clarify whether other Notch receptors such as Notch2 and Notch3 can be regulated by circRNAs in acute CNS injuries." (PMID 35392276, 2022). "In addition, qPCR and western blot revealed that after ischemic stroke, the expression of Notch1, Jagged1, and Hes1 mRNA and Notch1, Jagged1, NICD, and HES1 protein was significantly increased at D1 and D3 in NDI group." (PMID 34305641, 2021). "LncRNA GAS5 might aggravate the progression of ischemic stroke through miR-137 mediated Notch1 signaling pathway." (PMID 35087519, 2021). "Previous studies have reported that miR-137 could directly target on Notch1 and participate in diabetic kidney disease 35, ischemic stroke 36, and hypoxia-induced retinal ganglion cell apoptosis." (PMID 33046983, 2020). "However, it remains unclear whether the miR-449b/Notch1 signaling pathway is involved in the promotion of LRIC-induced neurogenesis following ischemic stroke." (PMID 36009031, 2022). "Our results showed that M2-sEV treatment decreased Notch 1 and increased Sox2 expression in activated astrocytes, suggesting that M2-sEVs might potentially be useful for astrocyte reprogramming to neuronal progenitor cells after ischemic stroke." (PMID 33391532, 2021).
ischemic stroke (continued). "Furthermore, VEGFA‐mediated neurovascular protection and Notch‐1‐triggered antiapoptotic effects in endothelium and other neural cells may synergistically contribute to neurovascular protection during the acute stage of ischemic stroke." (PMID 36786352, 2023). "This study was designed to clarify the role of myeloid Notch1 in CIRI, providing new therapeutic strategies for ischemic stroke." (PMID 38137105, 2023). "To further demonstrate that the Notch1 signaling pathway mediates LRIC and promotes neurogenesis after ischemic stroke, we injected Notch1 shRNA virus into the mouse SVZ to knockdown Notch1 expression." (PMID 36009031, 2022). "While PIN1 could facilitate the stability of Notch1 intracellular domain (NICD1) and promote the proapoptotic function of NICD1 following ischemic stroke." (PMID 37305740, 2023). "DAPT, as a γ-secretase inhibitor, can suppress Notch1 signaling activation, with several studies demonstrating that DAPT ameliorated brain damage and neurological deficits and inhibited proinflammatory cytokine secretion and microglial activation in an ischemic stroke model." (PMID 30646897, 2019).
oligodendroglioma (18 papers, 2013 to 2025). A well-differentiated (WHO grade II), diffusely infiltrating neuroglial tumor, typically located in the cerebral hemispheres. "It was also enriched for oligodendrogliomas (85%), mutations in NOTCH1, FUBP1, and CIC, and oligodendrocyte progenitor-specific expression." (PMID 32600353, 2020). "Both NOTCH1 mutations and 15q loss occur in a substantial subset of oligodendrogliomas and have previously been suggested as markers of poor prognosis in traditional risk models, providing support for our model." (PMID 30417117, 2018). "Our approach confirmed the association of NOTCH1 mutations with disease progression and shorter survival in oligodendroglioma, and further uncovered aberrant regulation of Notch and PI3K pathways as most strongly associated with advanced disease." (PMID 30417117, 2018). "Our results suggest inactivation of Notch signaling may be more relevant to oligodendroglioma progression than NOTCH1 mutations alone." (PMID 30417117, 2018). "Notch1 mutations have been shown to be activating in some cancers, but their role in the development of oligodendrogliomas as a tumor suppressor or oncogene is unknown." (PMID 23527265, 2013). "Therefore, inactivating point mutations of NOTCH1 are one of the most clinically meaningful alterations in oligodendroglioma progression and might suggest that inactivation of the Notch pathway is more generally responsible for poor clinical outcomes." (PMID 30417117, 2018). "Oligodendrogliomas were characterized by a common 1p/19q deletion and mutations in CIC, FUBP1, Notch1, and TERT promoters." (PMID 35572524, 2022). "NOTCH1 mutant oligodendrogliomas (n = 26) had higher cellular density than NOTCH1 wild-type tumors (n = 126) and this difference was the most significant among all mutations and CNAs (P = 0.0015)." (PMID 30417117, 2018). "Recombinant signal binding protein for immunoglobulin kappa-J region (RBPJ), the nuclear binding partner of activated NOTCH1’s intracellular binding domain (NICD), was mutated (n = 5) or homodeleted (n = 1) in 3% (6 of 169) of oligodendrogliomas." (PMID 30417117, 2018). "But the Notch1 gene has been widely assumed to be a driver gene in oligodendroglioma." (PMID 37533228, 2023). "However, it misses oligodendroglioma important pathogenic variants in p-TERT, CIC, FUBP, and NOTCH1." (PMID 37908227, 2023). "The gene set includes IDH1, IDH2, BRAF, CDKN2A/B, PTEN, and NOTCH1, but misses CIC, FUBP1, ATRX, and H3-3A important for oligodendroglioma and astrocytoma diagnosis." (PMID 37908227, 2023). "Several previous studies that aimed to identify prognostic indicators of oligodendroglioma proposed the use of CDKN2A/B, PTEN, NOTCH1, and other biomarkers as classification criteria to reclassify oligodendroglioma, but there is no consistent conclusion." (PMID 36588901, 2022). "Oligodendrogliomas exhibit a proneural genetic signature and the OG cells expressed NG2 and PDGFRα; however, they did not express the proneural markers Sox2, CD133, or Olig2 and only expressed low levels of Notch1 and nestin." (PMID 24278309, 2013). "Finally, after shRNA-mediated knockdown of NOTCH1, BT088 oligodendroglioma cells were not able to give rise to tumors in immunodeficient mice as cells slowly regressed over time." (PMID 33579922, 2021).
renal cell carcinoma (18 papers, 2009 to 2026). "Although the aberrant activation of NOTCH1 pathway causes a malignant progression of renal cell carcinoma (RCC), the precise molecular mechanisms behind the potential action of pro-oncogenic NOTCH1/HES1 axis remain elusive." (PMID 36973704, 2023). "Overexpression of Notch1 in mice with mutated VHL led to the development of renal cell carcinoma, structurally resembling the human pathology." (PMID 35055068, 2022). "While NOTCH1 dysregulation has been linked to renal cell carcinoma (RCC), its prognostic significance across RCC subtypes remains unclear." (PMID 42131103, 2026). "Selective suppression of Notch1 inhibited proliferation of renal cell carcinoma cells through a reduction in p-SAPK/JNK and p-p3847." (PMID 32764572, 2020). "The expression levels of Notch1 and Jagged1 were examined by western blot analysis and immunohistochemistry in pathologically identified clear cell renal cell carcinoma (RCC) and normal kidney tissues." (PMID 24959218, 2014). "It has been reported that miR-377-3P mediated the functions of circPDK1 in renal cell carcinoma (RCC) by binding to the 3′ untranslated region (UTR) of Notch1, indicating a critical role of miRNA between circRNA and Notch1 signaling." (PMID 35392276, 2022). "Notably, Notch1 expression is increased in CSCs—relative to non-stem tumor cells—from cancers such as renal cell carcinoma, TNBC, and glioma." (PMID 38745861, 2024). "However, in renal cell carcinomas, activation of the Notch pathway is independent of HIF-1α and HIF-2α, while in stem and precursor cells, hypoxia regulates Notch1 activity post-translationally via HIF-1α." (PMID 22363487, 2012).
aneurysm (17 papers, 2010 to 2024). Bulging or ballooning in an area of an artery secondary to arterial wall weakening. "We postulate that Notch1 deficiency in the SMCs decreases the CTGF expression thus protecting against the expansion of aneurysm." (PMID 28562688, 2017). "As a biomarker, circulating TGF-β1 is elevated in patients with Marfan syndrome, NOTCH1-associated aneurysm and BAV-associated aneurysm." (PMID 28993736, 2017). "Given the known role of endothelial Notch1 in mechanosensing of the aorta, it is tempting to speculate that EC-specific Notch1 signalling may predispose the descending aorta to aneurysms." (PMID 37909406, 2023). "Another BAV patient with aneurysm was carrying a heterozygous NOTCH1 variant (p.Thr123Met), which is considered as a polymorphism, and a heterozygous variant in the GATA5 gene (p.Leu233Pro), which has already been identified in one individual with BAV but without functional evidence." (PMID 36941270, 2023). "Although the mechanisms remain unclear, loss-of-function mutations in NOTCH1 predispose to hereditary forms of aneurysms that associate with aortic valve defects." (PMID 33514025, 2021). "In this study, therefore, the aneurysm mouse model with myeloid-specific knockout of Notch-1 was established to observe the role of Notch-1 in aneurysm progression." (PMID 38284891, 2024). "At the same time, the influence of Notch-1 on aneurysm formation was clarified, thereby providing new molecular mechanisms and potential intervention targets for aneurysm formation and progression." (PMID 38284891, 2024). "In this study, it was found that aneurysm tissues had massive macrophage infiltration and a high protein expression of Notch-1 in macrophages." (PMID 38284891, 2024). "In this study, the ApoE−/− chimeric mouse model was established to confirm that Notch-1 regulated the myeloid cell-mediated inflammatory response through the oxidative stress-SHP2 axis in aneurysm formation." (PMID 38284891, 2024). "Notch-1 disorders are important in the pathogenesis of atherosclerosis, aneurysm and inflammatory response." (PMID 38284891, 2024). "On the one hand, Notch1 appears to be activated in aortic aneurysms and either genetic or pharmacological attenuation of this pathway delays aneurysm progression." (PMID 30218064, 2018). "We also reported that reconstitution of bone marrow-derived cells from Notch1+/-;Apoe-/- mice (donor) in irradiated Apoe-/- mice (recipient) decreased the occurrence of aneurysm." (PMID 28562688, 2017). "It was found that after myeloid-specific knockout of Notch-1 in the aneurysm mouse model, the area of aneurysms and the macrophage infiltration were significantly reduced, the damage to arterial elastic plates was significantly relieved, and the oxidative stress level significantly declined." (PMID 38284891, 2024). "On the basis of these evidence, we hypothesised that metformin prescription might delay the progress of aneurysms through upregulating contractile phenotype in VSMCs via NOTCH 1 signalling." (PMID 33816448, 2021). "Aneurysm incidence could be reduced via Notch1 haploinsufficiency and pharmacological inhibition of NOTCH1 signaling through the prevention of macrophage accumulation to the aneurysm site." (PMID 32878347, 2020). "The opposite effects of SMC-specific Notch1 haploinsufficiency on Smad2 and Smad3 indicate that the crosstalk between Notch1 and Tgf-β signaling pathway in aneurysm may have differential effects on the downstream targets." (PMID 28562688, 2017). "Additionally, Notch 1 haploinsufficiency and pharmacological inhibition of Notch 1 signaling reduced the incidence of aortic aneurysms by preventing the accumulation of inflammatory cells to the aneurysm." (PMID 24834361, 2014). "Mutations in NOTCH1, a signaling pathway component important for the cardiac valve formation, have been found to cause complex congenital heart defects including BAV and have also been associated with BAV in the context of aneurysm." (PMID 20098615, 2010).
aneurysm (continued). "Thus, we suggested that metformin might delay the progress of aneurysms through enhancing the phenotype switch in VSMCs via NOTCH 1 signalling." (PMID 33816448, 2021). "No such histoarchitectural features of aneurysm were observed in the aortae of myeloid-Notch1+/-;Apoe-/- mice infused with AngII which displayed a well-defined lumen, no visible elastin fragmentation and minimal inflammatory cell infiltration." (PMID 28562688, 2017). "In conclusion, myeloid-specific knockout of Notch-1 can down-regulate the expression of TLR signaling pathway-related proteins, inhibit the oxidative stress level and increase the protein expression of SHP2, thereby relieving the development and formation of aneurysms." (PMID 38284891, 2024). "The diversified roles of Notch1 in various vascular cells demonstrate the complexity of Notch signaling and warrant studying the individual contributions of the Notch1 receptor in each vascular cell type on aneurysms." (PMID 28562688, 2017).